RBM48 (RNA binding motif protein 48)
Description:
As a component of the minor spliceosome, involved in the splicing of U12-type introns in pre-mRNAs.
Synonyms: C7orf64; HSPC304; DKFZp564O0523
Tractability: Small molecule: a structure with a bound ligand is known. PROTAC: ubiquitination databases record sites on it.
Gene: Protein-coding gene on chromosome 7 (92,528,773 to 92,540,481, forward strand). Ensembl gene ENSG00000127993.
Subcellular location (Human Protein Atlas): Nucleoplasm
Gene Ontology:
Molecular function: protein binding; nucleic acid binding
Biological process: mRNA splicing, via spliceosome
Cellular component: nucleoplasm; U12-type catalytic step 2 spliceosome
Genetic constraint (gnomAD): Loss-of-function variants: 21 observed, 21.53 expected, observed/expected ratio (o/e) 0.98, 90% interval 0.69 to 1.4. The upper end of that interval is the gene's LOEUF score, 1.4, which puts it in group 5 of 6, group 1 being the genes least tolerant of losing a copy. Missense variants: 310 observed, 326.44 expected, observed/expected ratio (o/e) 0.95, 90% interval 0.87 to 1.04. Synonymous variants: 105 observed, 116.43 expected, observed/expected ratio (o/e) 0.9, 90% interval 0.77 to 1.06.
Homologues: Orthologues: chimpanzee RBM48 (99% identical), macaque RBM48 (95% identical), dog RBM48 (84% identical), pig RBM48 (81% identical), guinea pig RBM48 (77% identical), rat Rbm48 (73% identical), mouse Rbm48 (72% identical), tropical clawed frog rbm48 (45% identical), zebrafish rbm48 (41% identical), Drosophila melanogaster CG34231 (17% identical).
Diseases named in the same sentence as RBM48 in open-access papers:
RBM48 is named in the same sentence as 2 diseases in open-access papers, as found by Europe PMC text mining. Sharing a sentence is not in itself a finding about the gene and the disease.
RBM48 shares sentences with these, for which no sentence is quoted: cancer (1 paper); cholestasis (1).